ZNF475 (zinc finger protein 475)
Gene: Protein-coding gene on chromosome 5 (122,129,622 to 122,184,959, forward strand). Ensembl gene ENSG00000250803.
Genetic constraint (gnomAD): Loss-of-function variants: 7 observed, 6.1 expected, observed/expected ratio (o/e) 1.15, 90% interval 0.64 to 1.85. That is too few expected variants to judge how well the gene tolerates losing a copy. Missense variants: 109 observed, 91.64 expected, observed/expected ratio (o/e) 1.19, 90% interval 1.02 to 1.39. Synonymous variants: 46 observed, 34.54 expected, observed/expected ratio (o/e) 1.33, 90% interval 1.05 to 1.7.
Homologues: Orthologues: chimpanzee ZNF474 (99% identical), mouse 1700034E13Rik (95% identical), guinea pig ZNF475 (94% identical), macaque ZNF475 (94% identical), tropical clawed frog znf474 (74% identical), Drosophila melanogaster CG30460 (15% identical), Drosophila melanogaster CG42675 (8% identical). Paralogues in human: ZNF474 (44% identical), ZC2HC1A (19% identical), ZC2HC1B (10% identical).
Diseases named in the same sentence as ZNF475 in open-access papers:
ZNF475 is named in the same sentence as 1 disease in open-access papers, as found by Europe PMC text mining. Sharing a sentence is not in itself a finding about the gene and the disease. The quoted sentences say what the papers report.
tumor (1 paper, 2023). "Previous studies have revealed that C2H2 zinc finger proteins such as zinc finger E-box-binding homeobox 1 (ZEB1), ZNF475 and ZNF568 could enhance tumor cell glycolysis." (PMID 36977688, 2023).